GASK1B (golgi associated kinase 1B)
Synonyms: C4orf18; ENED; FAM198B; AD021; FLJ38155; DKFZp434L142; AD036
Tractability: Antibody: UniProt predicts a signal peptide or a membrane-spanning region.
Gene: Protein-coding gene on chromosome 4 (158,124,474 to 158,174,249, reverse strand). Ensembl gene ENSG00000164125.
Subcellular location: Golgi apparatus membrane
Subcellular location (Human Protein Atlas): Nucleoplasm; Cytosol; Golgi apparatus; Nucleoli fibrillar center
Gene Ontology:
Cellular component: Golgi apparatus; Golgi membrane
Genetic constraint (gnomAD): Loss-of-function variants: 32 observed, 44.25 expected, observed/expected ratio (o/e) 0.72, 90% interval 0.55 to 0.97. The upper end of that interval is the gene's LOEUF score, 0.97, which puts it in group 4 of 6, group 1 being the genes least tolerant of losing a copy. Missense variants: 686 observed, 697.07 expected, observed/expected ratio (o/e) 0.98, 90% interval 0.92 to 1.05. Synonymous variants: 262 observed, 276.89 expected, observed/expected ratio (o/e) 0.95, 90% interval 0.86 to 1.05.
Homologues: Orthologues: chimpanzee GASK1B (95% identical), macaque GASK1B (93% identical), pig GASK1B (84% identical), mouse Gask1b (83% identical), rat Gask1b (82% identical), rabbit GASK1B (79% identical), dog GASK1B (70% identical), zebrafish gask1b (45% identical), tropical clawed frog gask1b (32% identical). Paralogues in human: GASK1A (31% identical).
Diseases named in the same sentence as GASK1B in open-access papers:
GASK1B is named in the same sentence as 9 diseases in open-access papers, as found by Europe PMC text mining. Sharing a sentence is not in itself a finding about the gene and the disease.
GASK1B shares sentences with these, for which no sentence is quoted: ovarian carcinoma (6 papers); tumor (6); cancer (4); lung adenocarcinoma (4); colorectal cancer (2); lung carcinoma (2); Anxiety (1); endometrial cancer (1); head and neck squamous cell carcinoma (1).